ALB (albumin)
Diseases named in the same sentence as ALB in open-access papers (continued):
Sharing a sentence is not in itself a finding about the gene and the disease.
Hearing impairment (5 papers, 2015 to 2025). A decreased magnitude of the sensory perception of sound. "Patients with hearing loss had a significantly higher median albuminuria of 300 mg albumin/gCrea compared to 45.8 mg albumin/gCrea in those with normal hearing (p ≤ 0.05)." (PMID 40165927, 2025). "At baseline five of the nine children with hearing loss were in stage I of AS (microalbuminuria: 30–300 mg albumin/g creatinine (gCrea)) and the remaining four hearing impaired children were in stage II of AS (proteinuria: >300 mg albumin/gCrea)." (PMID 33352923, 2020). "Given the inflammatory and microcirculation basis of the pathogenesis of SSNHL, it may be logical to assess ALB before initiating treatment in order to predict the prognosis of hearing loss." (PMID 34733230, 2021). "Patients with normal hearing (n = 28) showed a median albuminuria of 45.8 mg albumin/gCrea, while median albuminuria of children with hearing impairment (n = 8) was higher (300 mg albumin/gCrea)." (PMID 33352923, 2020). "Given that serum ALB level may be related to hemodynamic disorders, we included SSNHL patients with hearing impairment at all frequencies in this study." (PMID 34733230, 2021). "The risk parameters (urine albumin, urine creatinine, serum creatinine, BUN, SBP, and DBP) for kidney dysfunction were worse in the hearing-impairment group than in the no-hearing-impairment group." (PMID 26377178, 2015).
hemoglobinopathies (5 papers, 2011 to 2026). "Additionally, owing to its immunogenicity, only autologous serum can be employed; this precludes its use in patients with hemoglobinopathies, elevated total protein and albumin levels, or taking medications that may be injurious to the cornea, as well as in patients with positive microbial serology." (PMID 21311604, 2011).
hemophilia (5 papers, 2012 to 2023). Hemophilia is a genetic disorder characterized by spontaneous hemorrhage or prolonged bleeding due to factor VIII or IX deficiency. "Except for antihemophilic factors VIII and IX which are highly subsidized by the government and are free of charge for hemophilia patients, cost of IG and albumin should be borne by either insurance companies or patient." (PMID 23351278, 2012). "In the HIV-infected patients combined with hemophilia, the mean preoperative albumin and postoperative hemoglobin were found significantly lower than those in no-SSIs group (P<0.05)." (PMID 22583551, 2012).
hemorrhagic fever (5 papers, 2019 to 2025). An infectious disease caused by certain viruses or bacteria that can damage the walls of tiny blood vessels, making them leak, and can hamper the blood's ability to clot and cause severe, life-threatening illness. "Interestingly, increased BUN and decreased ALB levels were observed in neonates with hereditary thrombotic thrombocytopenic purpura, severe cases of Crimean-Congo hemorrhagic fever, and fatal cases of dengue hemorrhagic fever." (PMID 38806039, 2024).
hepatoblastoma (5 papers, 2015 to 2024). Hepatoblastoma (HB) is a malignant hepatic tumor and is the most common pediatric liver cancer. "Additionally, the effect of BTS extract on oleic acid–albumin-induced triglyceride accumulation in hepatoblastoma-derived HepG2 cells was significantly inhibited in a concentration-dependent manner." (PMID 38662301, 2024).
Hyperchloremia (5 papers, 2020 to 2026). An abnormally increased chloride concentration in the blood. "The most common acid–base influences identified in the hypokalemic group were an unmeasured ion effect, an alkalotic albumin effect and acidotic processes associated with hyperchloremia and hyperlactatemia." (PMID 40458759, 2025). "Our analysis also showed that hyperchloremia associated with reduced serum albumin." (PMID 32375681, 2020).
intrahepatic cholestasis (5 papers, 2016 to 2024). A cholestasis characterized by impairment of the bile flow caused by obstruction located in the liver. "The albumin–bilirubin score of the intrahepatic cholestasis of pregnancy group was significantly higher than the other groups." (PMID 39475920, 2024). "A positive, weak correlation was found between the albumin–bilirubin score and bile acid levels in the intrahepatic cholestasis of pregnancy group." (PMID 39475920, 2024). "The aim of this study was to examine the utility of the albumin–bilirubin score in cases of intrahepatic cholestasis of pregnancy." (PMID 39475920, 2024). "This study indicated higher albumin–bilirubin score levels in the intrahepatic cholestasis of pregnancy group and a positive relationship between serum bile acid levels and albumin–bilirubin score." (PMID 39475920, 2024). "The receiver operating curve curve analyses showed albumin–bilirubin score has significant performance for the prediction of intrahepatic cholestasis of pregnancy in all subjects (area under the curve: 0.726, 95%CI 0.679–0.774, p<0.001) (sensitivity: 69%, specificity: 64%)." (PMID 39475920, 2024). "Also, receiver operating curve analyses were performed to evaluate the predictive performance of the albumin–bilirubin score for intrahepatic cholestasis of pregnancy diagnosis." (PMID 39475920, 2024). "In our cohort, we found a prolonged elevation of markers for intrahepatic cholestasis (gGT and bilirubin), transaminases elevation, and a prolonged decrease of synthesis parameters (albumin, prothrombin time) correlating significantly with a high risk for postoperative cardiac hepatopathy." (PMID 33765046, 2021). "Therefore, albumin–bilirubin score could be a cost-effective liver function test for pregnant women with intrahepatic cholestasis of pregnancy." (PMID 39475920, 2024). "In addition, GGT is also an important indicator reflecting intrahepatic cholestasis, and the state of intrahepatic microcholestasis is involved in the development of MAFLD, so an elevated level of GGT or a decreased level of albumin will increase the risk of the development of MAFLD." (PMID 38491451, 2024). "Liver metabolism disorders occurred mainly as toxic hepatitis, intrahepatic cholestasis, or elevated levels of liver enzymes such as total bilirubin (t-Bil), aspartate aminotransferase (AST), alanine transaminase (ALT), ALB, and globulin (GLB)." (PMID 27796328, 2016).
iron overload (5 papers, 2019 to 2025). "Although adjustments for albumin and C-reactive protein were tried to screen out highly inflammatory status as a cause of high ferritin, we cannot completely exclude causes of high ferritin other than iron overload due to lack of thorough clinical information about these factors." (PMID 36650247, 2023). "Glycated Albumin correlated with hepatic and heart iron accumulation but not with pancreatic iron overload." (PMID 40924301, 2025). "Moreover, an inverse correlation observed between serum albumin and ALT levels is also indicative of decreased synthetic function of the liver parenchyma, in cases with iron overload." (PMID 39416629, 2024).
lactic acidosis (5 papers, 2012 to 2025). Metabolic acidosis characterized by the accumulation of lactate in the body. "Low albumin concentrations may be associated with the accumulation of coelomic fluid (ascites) that has a high concentration of bicarbonate, which acts as a buffer against lactic acidosis (e.g., associated with deep dives)." (PMID 22359635, 2012). "For fluid maintenance, lactic acidosis can be avoided by the replacement of Ringer’s lactate with PlasmaLyte and albumin." (PMID 40861658, 2025). "Compared with AG, after its correction for the effect of albumin, ACAG can more accurately determine occult organizations, be more conducive to the diagnosis of high lactic acidosis, and more accurately determine the type of acid–base metabolism turbulence." (PMID 40631543, 2025). "In the present study, the ability of an albumin hemodialysis system (ADVOS multi) to correct hypercapnic and lactic acidosis in vitro has been demonstrated." (PMID 31535309, 2019). "Linezolid treatment resulted in lactic acidosis, increased serum levels of AST, ALT, urea, creatinine, and albumin, and oxidative stress characterized by decreased catalase activity and reduced glutathione (GSH) associated with increased nitric oxide (NO) malondialdehyde (MDA)." (PMID 40529491, 2025).
lymphangiectasia (5 papers, 2021 to 2024). "The increased 51Cr albumin stool clearance led to a diagnosis of secondary intestinal lymphangiectasia with PLE, and the patient underwent a specific diet therapy." (PMID 39274362, 2024). "In the case of Patient 5 who had presented with severely refractory lymphangiectasis, his albumin level was still low at 3.1 g/dL with sirolimus use, but he no longer needed paracentesis or thoracentesis." (PMID 33407260, 2021). "Low blood albumin level is the most consistent finding in lymphangiectasia." (PMID 34679072, 2021).
lymphedema (5 papers, 2018 to 2024). Excess fluid collection in tissues, causing swelling. "The link between ISL stage 3 and low albumin suggests that advanced lymphedema, as a chronic inflammatory condition, exacerbates nutritional deficiencies." (PMID 39529928, 2024). "Considering that the cohort of this study consists of long-term cancer survivors, it is important to note that lymphedema itself can influence albumin levels and PNI scores." (PMID 39529928, 2024). "The increased level of lymphedema in primary tumor tissues of MMTV-PyMT; PDPN-tk mice was confirmed by albumin immunohistochemistry." (PMID 30592710, 2018).
meningioma (5 papers, 2014 to 2024). A generally slow growing tumor attached to the dura mater. "A recent retrospective study of 503 meningioma patients identified tumor area, preoperative albumin concentration, and preoperative platelet count as independent predictors for higher intraoperative blood loss." (PMID 39267835, 2024).
mood disorder (5 papers, 2014 to 2024). A cognitive disorder a disturbance in which the person's mood is hypothesized to be the main underlying feature. "The similarity in IL-6, Zn, CRP, and albumin levels between UD and BD during depressive episodes of similar severity suggests common underlying pathophysiological processes in mood disorders." (PMID 38785543, 2024). "The finding of significantly lower albumin levels in mood disorder patients compared to healthy controls underscores the impact of these conditions on systemic health." (PMID 38785543, 2024). "Four biological parameters were selected that in earlier research were found to be associated with inflammatory events in mood disorders: IL-6, CRP, Zn, and albumin levels." (PMID 38785543, 2024). "A meta-analysis of inflammatory biomarkers in the CSF of patients with mood disorders found that total protein, albumin, and AQs were higher in patients with mood disorders than in healthy controls." (PMID 34021122, 2021). "Lower albumin levels in patients could indicate a state of chronic inflammation or altered metabolism, a common occurrence in mood disorders." (PMID 38785543, 2024). "Furthermore, the similarity in albumin levels across these groups might reflect a shared aspect of metabolic alteration in mood disorders." (PMID 38785543, 2024).
muscle ache (5 papers, 2016 to 2025). "In summary, male sex, any coexisting disease, symptoms of cough, muscle ache, and diarrhea, laboratory abnormalities of decreased lymphocyte/albumin and increased CRP level are risk factors for severe/critical COVID‐19." (PMID 32397011, 2020). "Multiple logistic regression analysis and receiver operating characteristic (ROC) curve found that fatigue, myalgia, low hemoglobin levels, low albumin levels, elevated ALT levels, and elevated AST levels are all predictors for Chlamydia psittaci pneumonia, with excellent predictive performance." (PMID 40236451, 2025). "These patients were older, more frequently had polymyalgia rheumatica/giant cell arteritis or cancer, and received a higher dosage of glucocorticoids than those with no lymphocyte count and albumin level available." (PMID 27218256, 2016).
pancreatic disease (5 papers, 2016 to 2025). "We also found that anemic patients had lower albumin, but we treated it as a co-existing disorder caused by pancreatic diseases and nutritional changes." (PMID 35646973, 2022). "emphasised the clinical value of preoperative immunonutrition for reducing complications and length of stay (LOS) and improving postoperative nutritional indices (e.g., the NRI and serum albumin concentration) in patients with advanced pancreatic disease." (PMID 41346728, 2025). "On the other hand, higher values of albumin (OR: 0.94, 95CI%: 0.896-0.987, P=0.013), urea (OR: 0.996, 95CI%: 0.993-0.999, P=0.014 and high density lipoprotein (OR: 0.419, 95%CI: 0.187-0.941, P=0.035) were also as proved as predictors of DM among pancreatic disease." (PMID 35937787, 2022). "Recently, a three-marker signature based on levels of CA19-9, IGF-1, and albumin has shown a sensitivity of 93.6% and specificity of 95% when differentiating PDAC patients from other pancreatic diseases." (PMID 27689078, 2016).
paroxysmal AF (5 papers, 2022 to 2025). "In conclusion, our study indicates that low ALB levels in male patients are independently associated with paroxysmal AF." (PMID 36031606, 2022). "After adjustment for all confounding factors, ALB in male patients was significantly associated with paroxysmal AF (odds ratio [OR] 0.889, 95% confidence interval [CI] 0.832–0.950; p < 0.001)." (PMID 36031606, 2022). "Admittedly, it would be interesting to perform a prospective cohort design to evaluate the association between serum ALB levels and paroxysmal AF in the future." (PMID 36031606, 2022). "Nevertheless, further subgroup analysis suggested the different associations between ALB levels and blood lipid profiles in paroxysmal AF by gender." (PMID 36031606, 2022). "Pearson correlation analysis was used to study the correlation between ALB and blood lipid profiles, multivariate regression models were performed to investigate the association between ALB and paroxysmal AF." (PMID 36031606, 2022). "This retrospective study aimed to explore the association between ALB levels and paroxysmal AF by gender in a Chinese population." (PMID 36031606, 2022). "Hereby, in this case–control study, we aim to characterize the association between the ALB levels and paroxysmal AF by gender in 915 patients from China." (PMID 36031606, 2022). "We hypothesized that low serum ALB is associated with paroxysmal AF, the confirmation of this hypothesis has significant clinical value because serum ALB is adjustable." (PMID 36031606, 2022). "We reported herein an association between low serum ALB levels and paroxysmal AF." (PMID 36031606, 2022). "However, there is an unclear association between serum albumin (ALB) and gender in paroxysmal AF patients." (PMID 36031606, 2022). "The results showed that albumin levels were significantly lower in both men and women with AF (P < 0.05), particularly in cases of paroxysmal AF." (PMID 38580915, 2024). "We adjusted for these confounders as much as possible and analyzed the difference in ALB levels among these comorbidities of paroxysmal AF." (PMID 36031606, 2022). "The results showed that there was a positive correlation between ALB levels and blood lipid profiles in patients with paroxysmal AF, including TG (r = 0.212, p < 0.001), TC (r = 0.381, p = 0.002), HDL-C (r = 0.329, p < 0.001), and LDL-C (r = 0.263, p < 0.001)." (PMID 36031606, 2022). "Certainly, it is necessary to further explore the specific relationship between serum ALB levels and isolated paroxysmal AF." (PMID 36031606, 2022). "Our current finding suggested that low serum low ALB levels in male patients were associated with paroxysmal AF; there was a positive correlation between ALB levels and blood lipid profiles in patients with paroxysmal AF." (PMID 36031606, 2022). "Compared with the control group, ALB levels in male and female patients with paroxysmal AF were significantly lower (p < 0.001)." (PMID 36031606, 2022). "Compared with controls, ALB levels in aged ≤ 60 years and aged > 60 years patients with paroxysmal AF were significantly lower (P < 0.001)." (PMID 36031606, 2022). "Nevertheless, the current results didn’t support a significant difference in ALB levels among the comorbidities of paroxysmal AF." (PMID 36031606, 2022). "Nevertheless, further analyses didn’t support a significant difference in ALB levels among the comorbidities of paroxysmal AF." (PMID 36031606, 2022). "The results indicated that lower ALB in male and female patients with paroxysmal AF had lower TC and LDL-C (p < 0.001)." (PMID 36031606, 2022). "Even more so, it is possible that lower serum ALB and blood lipid profiles were jointly involved in the pathologic progression of paroxysmal AF." (PMID 36031606, 2022). "Interestingly, we also observed that there was a positive correlation between ALB levels and blood lipid profiles in patients with paroxysmal AF." (PMID 36031606, 2022).
paroxysmal AF (continued). "Additionally, lower ALB in male patients with paroxysmal AF had lower TG (p < 0.05) and lower HDL-C in female patients (p < 0.05)." (PMID 36031606, 2022). "However, we analyzed the difference in ALB levels among the comorbidities of paroxysmal AF and adjusted for them in our logistic models." (PMID 36031606, 2022). "Second, the causal association between ALB levels and paroxysmal AF could not be determined due to the case–control design." (PMID 36031606, 2022). "After adjusting for age, TG, TC, LDL-C and HDL-C, Scr, AST, ALT, ALB, APOA1, APOB, and PAB, SUA remained significantly correlated with paroxysmal AF (OR = 1.161, 95% CI 1.039–1.298, P = 0.008)." (PMID 35726017, 2022). "Although these studies imply a close relationship between low serum ALB and AF, paroxysmal AF, which was often not adequately considered." (PMID 36031606, 2022).
penile cancer (5 papers, 2017 to 2024). A primary or metastatic malignant neoplasm that affects the penis. "No statistically significant trends were seen between the included serum inflammatory markers and risk of penile cancer, but higher albumin levels were associated with an increased risk of testicular cancer [HR for albumin (g/L): 1.10 (95% CI: 1.03–1.18)]." (PMID 28900475, 2017). "No statistically significant trends were seen between serum inflammatory markers and risk of penile cancer, but higher albumin levels increased the risk of testicular cancer [HR for albumin (g/L): 1.10 (95% CI: 1.03–1.18)]." (PMID 28900475, 2017). "Background and Objectives: To investigate the role of preoperative albumin-to-alkaline phosphatase ratio (AAPR) in predicting pathologic node-positive (pN+) disease in penile cancer (PC) patients undergoing inguinal lymph node dissection (ILND)." (PMID 38541140, 2024). "A study investigating penile cancer patients undergoing inguinal lymph node dissection (ILND) revealed that the preoperative albumin alkaline phosphatase ratio (AAPR) reliably predicts pathologic lymph node-positive (pN+) status." (PMID 39359427, 2024). "For instance, in penile cancer, the albumin-to-alkaline-phosphatase ratio might predict lymph node involvement." (PMID 38610718, 2024).